BRCA1 (BRCA1 DNA repair associated)
Diseases named in the same sentence as BRCA1 in open-access papers (continued):
Sharing a sentence is not in itself a finding about the gene and the disease.
ovarian carcinoma (continued). "First application of next‐generation sequencing in Moroccan breast/ovarian cancer families and report of a novel frameshift mutation of the BRCA1 gene." (PMID 27896281, 2016). "Gene mutation and loss of protein expression reportedly exist in breast and ovarian cancer and the loss and dysfunction of the BRCA1 protein induced by BRCA1 promoter hypermethylation have been identified in breast and ovarian cancer." (PMID 27410681, 2016). "The combined prevalence of BRCA1/2 germline and somatic mutations in patients with ovarian cancer differs according to the detection method used." (PMID 27907908, 2016). "Approximately 8–15% epithelial ovarian cancer patients are BRCA1 or BRCA2 germline mutation carriers." (PMID 27914478, 2016). "Poly (ADP-ribose) polymerase (PARP) inhibitor (PARPi) olaparib has been approved for treatment of advanced ovarian cancer associated with BRCA1 and BRCA2 mutations." (PMID 27498558, 2016). "To summarise, our findings confirm previous reports that improved overall survival associated with BRCA1 mutations carried in ovarian cancer patients." (PMID 26753012, 2016). "The BRCA1 mutation reduced the likelihood of death in ovarian cancer by 86 % (HR 0.14; CI: 0.032-0.650, p = 0.012)." (PMID 26753012, 2016). "Genetic inactivation of the major hereditary breast/ovarian cancer predisposition HR genes BRCA1 or BRCA2, or of other HR genes such as the Rad51 paralogs Rad51C, XRCC2 or XRCC3 biases HR in favor of LTGC." (PMID 27832076, 2016). "The risk of developing ovarian cancer in BRCA1-mutation carriers is minor before the age of 40 but then also shows a continuous rise." (PMID 27881737, 2016). "The lifetime risk of developing ovarian cancer is 40–60 and 11–27% for BRCA1 and BRCA2 mutation carriers, respectively." (PMID 27242959, 2016). "Breast-feeding, oral contraceptive use, and parity are associated with decreased risk of developing ovarian cancer in BRCA1/2 mutation carriers." (PMID 27588493, 2016). "The mean age at diagnosis of ovarian cancer in patients with germ line BRCA1 mutations is younger than for patients with sporadic cancer." (PMID 27350785, 2016). "A total of 133 unrelated patients with personal and family histories of breast and/or ovarian cancer underwent BRCA1 and BRCA2 germline mutation screening." (PMID 26852015, 2016). "In contrast, the European Medicines Agency (EMA) approved olaparib for ovarian cancer patients who have either germline or somatic BRCA1/2 mutations." (PMID 27907908, 2016). "A defects in BRCA1/2 is one of the important causes of cancer development, especially of breast and ovarian carcinomas." (PMID 27643881, 2016). "Next antioncogene BRCA1 is linked to the etiology of hereditary of familial breast and ovarian cancer." (PMID 27405474, 2016). "Another commonly mutated gene in breast and ovarian cancers, functional BRCA1 protects the cell from double-stranded DNA damage through homologous recombination." (PMID 27213343, 2016). "Several studies have focused on clinical and pathological features of breast and ovarian cancer associated with BRCA1 and BRCA2 mutations." (PMID 27129401, 2016). "BRCA1 germline mutations reduced by 86 % likelihood of death in our ovarian cancer patients (HR 0.14 [CI: 0.032–0.650], p = 0.012)." (PMID 26753012, 2016). "The ovarian cancers that predominantly develop in BRCA1 and BRCA2 mutation-carriers are of serous or endometrioid histology and of high grade." (PMID 27468354, 2016). "Among epithelial ovarian cancer patients unselected for family history of cancer, 19% were BRCA1/2 germline mutation carriers." (PMID 27914478, 2016).
ovarian carcinoma (continued). "Based on a cohort of 316 ovarian cancer patients taken from TCGA, 77.8 % had BRCA1/2 wild type, 8.5 % had germline mutations, 3.1 % had somatic mutations, and 10.4 % had BRCA1 hypermethylation." (PMID 26753012, 2016). "In contrast to the general population, in which the lifetime risk of developing ovarian carcinoma is 1.6% (average age at diagnosis 63 years), women carrying a BRCA1 mutation have a lifetime risk of 35–60% with an average age of diagnosis of 50 years." (PMID 27463617, 2016). "We also have reported that higher BRCA1 expression is associated with chemosensitivity in ovarian cancer patients, and ovarian cancer patients with BRCA dysfunction tend to have a better outcome." (PMID 26675546, 2016). "Population-based genome wide association studies have identified a locus at 9p22.2 associated with ovarian cancer risk, which also modifies ovarian cancer risk in BRCA1 and BRCA2 mutation carriers." (PMID 27463617, 2016). "Our findings provide the basis for the development of primary ovarian cancer prevention strategies in BRCA1/2 mutation carriers." (PMID 27216078, 2016). "The Cancer Genome Atlas project and University of Washington Medical Center revealed that 6.3%-6.8% of patients with ovarian cancer carried somatic BRCA1/2 mutation." (PMID 27257965, 2016). "In ovarian cancer patients, somatic mutations together with germline mutations in BRCA1/2 genes were associated with favorable survival." (PMID 27257965, 2016). "We comprehensively characterized the associations of genetic variants in the region with ovarian cancer risk for BRCA1 and BRCA2 mutation carriers." (PMID 27463617, 2016). "BRCA1/2 mutations were seen in 35.5% of the patients with first and/or second-degree relatives with breast and/or ovarian cancer." (PMID 27914478, 2016). "Following genotype imputation, ovarian cancer associations were assessed for 4,873 and 5,020 SNPs in BRCA1 and BRCA 2 mutation carriers respectively, within a retrospective cohort analytical framework." (PMID 27463617, 2016). "Women with confirmed mutations in the BRCA1 gene should be referred for a comprehensive medical examination for the early detection of breast and ovarian cancers or recieve preventive medical interventions." (PMID 29138730, 2016). "In a study of 200 Polish families with three or more breast or ovarian cancers a BRCA1/2 mutation was identified in 64 %; the prevalence of BRCA1 mutations was 60 % and the prevalence of BRCA2 mutations was 4 %." (PMID 26843898, 2016). "We screened 121 women with familial and/or early-onset breast or ovarian cancer for mutations in BRCA1, BRCA2 and PALB2." (PMID 26843898, 2016). "In Colombia, a study conducted by Torres and collaborators found a frequency of 24.5% of deleterious BRCA1/BRCA2 mutations in a cohort of 53 breast/ovarian cancer families evaluated." (PMID 27741520, 2016). "This work provides a rationale for combining BRCA2 ASO and olaparib treatment and extends the applicability of olaparib clinically, which up until now has been used primarily in the context of BRCA1 or 2 mutated ovarian cancers." (PMID 26959114, 2016). "The risk of ovarian carcinoma at 70 years old was reported as 39% and 11% with BRCA1 and BRCA2 mutation, respectively." (PMID 27643881, 2016). "Comparison of olaparib vs. pegylated liposomal doxorubicin (PLD) in recurrent BRCA1/2-associated ovarian cancer produced similar results for both drugs." (PMID 27555886, 2016). "(ii) One female carried a frameshift deletion (rs80357735) in BRCA1 that is predicted to result in a significantly increased risk for breast and ovarian cancer." (PMID 27930734, 2016). "We also show that BRCA1 germline mutations are associated with good prognosis for patients with ovarian cancer and OS was better for carriers of BRCA1 mutations (HR 0.14, 95 % CI: 0.032–0.650, p = 0.012) than for noncarriers." (PMID 26753012, 2016).
ovarian carcinoma (continued). "In this cohort of epithelial ovarian cancer patients, the prevalence of BRCA1/2 mutation was 19%, mostly detected in different gene locations." (PMID 27914478, 2016). "In this cohort of 133 familial breast/ovarian cancer patients, 13 deleterious mutations in BRCA1 were found in 18 unrelated patients, including five mutations that were reported in our previous study." (PMID 26852015, 2016). "Several studies suggest that sporadic ovarian carcinomas with somatic mutations in BRCA1/2 also display differential response to platinum treatment with improved survival." (PMID 27191893, 2016). "The prevalence of BRCA1/2 mutations is relatively low compared to previous studies of Polish breast and/or ovarian cancer families, in large part due to the low frequency of BRCA1 mutations." (PMID 26843898, 2016). "The opportunity to review and revise genetic screening and testing practices will identify opportunities, where universal adoption of BRCA1/2 mutation testing will impact and improve treatment of women with ovarian cancer." (PMID 27242959, 2016). "Women with inherited BRCA1 mutations have an elevated risk (40-80%) for developing breast and ovarian cancers." (PMID 27246982, 2016). "Associations between selected SNPs from 9p22.2 and ovarian cancer in BRCA1, BRCA2 and combined analysis of BRCA1/2 mutation carriers." (PMID 27463617, 2016). "The 9q13 band is a known fragile site that is commonly involved in pericentric inversions in the germline linked with ovarian cancer, while 4q13 has been found to have a high rate of copy number variation in BRCA1 associated ovarian cancers." (PMID 26264669, 2016). "The estimated lifetime risk of ovarian cancer in BRCA1 mutation carriers is 40% to 50%, among BRCA2 mutation carriers the risk is lower, ranging from 20% to 30%, while the lifetime risk of ovarian cancer in the general population is 1.6%." (PMID 27350785, 2016). "Both univariate and multivariate analyses show that the BRCA gene status dychotomizes ovarian cancer patients to better and worse prognosis for overall survival (BRCA1 germline mutations constitute better prognosis than BRCA1 wild type)." (PMID 26753012, 2016). "In particular, one of the most recent examples was described by our group for a SNP (rs2304277) in the OGG1 (8-guanine DNA glycosylase) gene that was associated with increased ovarian cancer risk in BRCA1 mutation carriers." (PMID 27015555, 2016). "Approximately half of the pathogenic variants identified in patients with breast or ovarian cancer were in genes other than BRCA1/2." (PMID 26681312, 2016). "A recent phase I study of AZD1775, an inhibitor of the Wee1 G2 checkpoint kinase, administered as a single agent, demonstrated partial responses in patients with refractory solid tumors, including a patient with BRCA1/2-mutated ovarian cancer." (PMID 27983698, 2016). "On December 2014 the European Medicines Agency (EMA) and the U.S.A. Food and Drug Administration (FDA) approved the PARPi olaparib for treatment of BRCA1/BRCA2 mutated ovarian cancer." (PMID 26745875, 2016). "This property has been successfully translated into the clinic for breast and ovarian cancer patients with mutations in the tumor suppressor genes, BRCA1 or BRCA2." (PMID 26910887, 2016). "The BRCA1 protein is encoded by the tumor suppressor gene BRCA1, mutation in which occurs often in breast and ovarian cancer patients." (PMID 27277344, 2016). "In this study, age appeared to have a marked influence on the BRCA1 mutation frequency in familial breast/ovarian cancer patients diagnosed with TNBC." (PMID 27553291, 2016). "Other studies confirmed statistically significant high contribution of three founder BRCA1 mutations in Polish breast/ovarian cancer patients." (PMID 26779294, 2016). "About 10% of all breast and ovarian cancers are dominantly inherited mainly by mutations in the BRCA1 and BRCA2 genes." (PMID 27974137, 2016).
ovarian carcinoma (continued). "Women harboring BRCA1/2 germline mutations have high lifetime risk of developing breast/ovarian cancer." (PMID 27553291, 2016). "In this cohort, 19 out of 100 unselected Brazilian ovarian cancer patients, were BRCA1/2 mutation carriers, mainly in the BRCA1 gene (n = 17)." (PMID 27914478, 2016). "While the lifetime cumulative risk of breast or ovarian cancer is high for BRCA1/2 mutation carriers, the actual risk conferred by a particular mutation is difficult to estimate." (PMID 27769273, 2016). "Among 71 Jewish patients with ovarian cancer, 22 had BRCA1 three germline mutations and one truncating mutation, and 12 had BRCA2 truncating mutations vs 37 patients with sporadic ovarian cancer." (PMID 26753012, 2016). "The overall prevalence of germline BRCA1/2 mutations is estimated between 11% and 15% of all ovarian cancers." (PMID 27167707, 2016). "On the contrary, overexpression of BRCA1 was associated with increased apoptosis and inhibition of cell growth in breast and ovarian cancer cells." (PMID 27356740, 2016). "We aim to investigate the occurrence of BRCA1/2 mutations in 99 Taiwanese patients with ovarian cancer which included serous (n = 46), endometrioid (n = 24), and clear cell (n = 29) carcinomas." (PMID 27907908, 2016). "Data were available for 15,252 BRCA1 mutation carriers of whom 2,462 were censored at ovarian cancer diagnosis." (PMID 27463617, 2016). "Ovarian cancer in HBOC is often diagnosed at a younger age compared with sporadic ovarian cancer, in particular for patients with BRCA1 mutation." (PMID 27350785, 2016). "The BRCA1 exon 11 mutation is clearly pathogenic and is associated with an increased risk of early onset breast and/or ovarian cancer." (PMID 26884819, 2016). "BRCA1 mutation was detected in one out of three patients diagnosed with ovarian cancer and in four out of nine with both breast and ovarian cancer." (PMID 27914478, 2016). "Identifying more strongly associated variants with ovarian cancer in the 9p22.2 region relative to the initial GWAS hit in BRCA1 and BRCA2 mutation carriers will refine the cancer risks associated with this locus further." (PMID 27463617, 2016). "Here, we assessed 25 pathogenic and 15 neutral missense variants of the BRCA1 breast/ovarian cancer susceptibility gene in four BRCA1 functional assays." (PMID 27272900, 2016). "Evidence of serous tubal intraepithelial carcinoma in risk-reducing salpingo-oophorectomy of asymptomatic women with known BRCA1 or BRCA2 mutations or strong family history of breast or ovarian cancer." (PMID 27200296, 2016). "The 9p22 locus was first found to be associated with ovarian cancer risk in the general population, and subsequently to be an ovarian cancer risk modifier in BRCA1 and BRCA2 mutation carriers." (PMID 27463617, 2016). "It has been noticed that mutations in tumor suppressor genes; such as BRCA1 in ovarian cancer, have a significant function in DNA damaging related apoptosis in cancer chemotherapy." (PMID 27195613, 2016). "Between 2002 – 2008, 125 consecutive patients with ovarian cancer were categorized as having three founder mutations in the BRCA1 gene in Poland as: 5382insC [exon 20], 4153delA [exon 11.17], and 300 T > G [exon 5]." (PMID 26753012, 2016). "Higuchi looked at CTLA-4 blockade with PARPi ABT-888(Veliparib) in BRCA1-deficient murine ovarian cancer models and showed that combination CTLA-4/PARPi was able to provide therapeutic benefit in these experiments supporting further clinical investigations." (PMID 27231574, 2016). "One of the risk factors for ovarian cancer is germline mutations in BRCA1 or BRCA2 genes, accounting for approximately 8–15% of ovarian cancer cases worldwide." (PMID 27914478, 2016). "We have recently shown that rs2304277 variant in the OGG1 glycosidase gene of the Base Excision Repair pathway can increase ovarian cancer risk in BRCA1 mutation carriers." (PMID 27015555, 2016).
ovarian carcinoma (continued). "Friedenson has summarized these reports, analyzing data from more than 30 epidemiological studies on the incidence of other than the breast or ovarian cancers in BRCA1 and BRCA2 mutation carriers and in large populations eligible for mutation testing." (PMID 26779294, 2016). "The most important genes in the context of genetic counseling for ovarian cancer susceptibility are BRCA1 and BRCA2, which account for approximately 24% of the familial risk among first-degree relatives." (PMID 27463617, 2016). "Familial breast and ovarian cancers are linked to highly penetrant mutations in the BRCA1/2 susceptibility genes that overall account for 20–25 % of hereditary breast cancers and 15 % of ovarian cancers." (PMID 27599564, 2016). "Women who have mutations in the BRCA1 gene have an increased lifetime risk of developing hereditary breast and ovarian cancers." (PMID 28164176, 2016). "Rebbeck's results show that the proportion of cancer-affected individuals carrying mutated BRCA1 with BC was 72.9%, with OC 18.7% and with a personal history of breast and ovarian cancer was 8.4%." (PMID 27741520, 2016). "The aim of this study was to evaluate BRCA1/2 mutations, through entire gene sequencing, in a Brazilian population of women with epithelial ovarian cancer." (PMID 27914478, 2016). "BRCA1 c.3331_3334delCAAG mutation in exon 11, is also a frequent mutation in ovarian cancer patients from Colombia and Spain, but mostly rare in Canadian patients." (PMID 27914478, 2016). "Mutations or defects in BRCA1/2 are closely related with early development of breast and ovarian carcinomas." (PMID 27643881, 2016). "Many reports suggest that the outcomes of treatment for ovarian cancer (OC) differ between patients who are carriers of BRCA1/2 mutations and patients with sporadic OC (SOC)." (PMID 26807161, 2016). "Genotype data were available for 15,252 (2,462 ovarian cancer cases) BRCA1 and 8,211 (631 ovarian cancer cases) BRCA2 mutation carriers." (PMID 27463617, 2016). "Patients harbouring a deleterious change in BRCA1 have a significantly increased risk of developing breast and or ovarian cancer." (PMID 26884819, 2016). "In BRCA1 mutation carriers one set of eight correlated candidate causal variants for ovarian cancer risk modification was identified (top SNP rs10124837, HR: 0.73, 95%CI: 0.68 to 0.79, p-value 2× 10−16)." (PMID 27463617, 2016). "We identified a BRCA1/2 mutation in 21 (17.4 %) of 121 patients with familial and/or early-onset breast or ovarian cancer from Southern Poland." (PMID 26843898, 2016). "Since BRCA1 mutation carriers are at high risk of ovarian cancer, it will be important to also explore the role of RANKL/RANK blockade in ovarian carcinogenesis." (PMID 27241552, 2016). "The breast and ovarian cancer susceptibility gene BRCA1 encodes a multifunctional tumor suppressor protein BRCA1, which is involved in regulating cellular processes such as cell cycle, transcription, DNA repair, DNA damage response and chromatin remodeling." (PMID 27277344, 2016). "Based on these properties, poly(ADP-ribose) polymerase (PARP) inhibitors are used for treatment of cancers, such as BRCA1/2 mutated breast and ovarian cancers, or certain solid cancers in combination with anti-cancer drugs." (PMID 26927065, 2016). "In support of this possibility, differences in the association patterns with ovarian cancer between BRCA1 and the general population have been reported before." (PMID 27463617, 2016). "We show here that the status of the variants identified in the BRCA1 breast/ovarian cancer susceptibility gene can be estimated thanks to experimental systems using yeast cells and a novel computational model." (PMID 27272900, 2016). "Approximately 15% of ovarian cancer patients have a germline BRCA1 or BRCA2 mutation which has substantial implications for their personal management and that of their relatives." (PMID 27406733, 2016).